AFP (alpha fetoprotein)
Diseases named in the same sentence as AFP in open-access papers (continued):
Sharing a sentence is not in itself a finding about the gene and the disease.
tumor (continued). "The results showed that CTC-WBC clusters and tumor size (P = 0.001), tumor number (P = 0.005), portal vein tumor thrombus (P = 0.026), BCLC stage (P < 0.001), AFP level (P = 0.002), and total number of CTCs (P < 0.001) were statistically related." (PMID 33224869, 2020). "Cox regression and ROC analysis were conducted as observed, and four out of six tumour biomarkers, CA15‐3 and AFP being the exception, were independent predictors of all‐cause mortality." (PMID 32372544, 2020). "Encouragingly, regarding the prediction of EC occurrence, the PPARγ/ERRα ratio is superior not only to PPARγ or ERRα alone but also to currently used clinical serum tumor markers, namely, CA125, CA199, CA153, AFP and CEA." (PMID 33197888, 2020). "A multivariable analysis was performed and the results showed that CTC-WBC clusters (HR = 1.951, 95% CI: 1.348–2.824, P < 0.001), tumor size, portal vein tumor thrombus, BCLC stage, AFP and total CTC number were independent predictors of DFS." (PMID 33224869, 2020). "We constructed a prognostic nomogram including NUDT1 expression, and clinical factors, such as, AFP levels, vascular invasion, Child–Pugh classification, age, sex, AJCC staging, and tumor differentiation." (PMID 32341205, 2020). "In patients with an ALT level > 2 ULN, the AFP/(ALT × AST) ratio (AUC 0.769; 95% CI 0.700-0.829) was better than the AFP tumor (P < 0.001) marker in diagnosing HCC, with its sensitivity and specificity significantly increasing." (PMID 33490235, 2020). "The serum tumor markers β-hCG, LDH and AFP are already part of the TNM classification (UICC, 2016, 8th edition) thus influence the staging of tumors in clinical practice." (PMID 32235691, 2020). "Although the tumor markers in our case were within th reference values range, β-HCG, AFP, LDH, and CA-125 should be measured in all young women who present with a pelvic mass." (PMID 32483810, 2020). "AFP levels in HCC patients have strong relationships with unfavorable tumor features (such as histological grade, tumor size, and vascular invasion) and staging classification." (PMID 32923383, 2020). "Our explanation is that AFP is also regulated by persistence of HBV activation, sex, and tumor size." (PMID 32150664, 2020). "Traditional serum markers have been proved as potential tumor markers for prognostic in HCC, such as alpha-fetoprotein (AFP)." (PMID 32518728, 2020). "Serum tumor marker examination was preoperatively performed for all patients and the positive rate of CA-125, CA-199, CEA, AFP were 28.6% (2/7), 14.3% (1/7), 14.3% (1/7), 0% (0/7), respectively." (PMID 32899024, 2020). "In our study, twenty-six patients with localized TGCT had preoperative increased serum tumor markers (elevated HCG and/or AFP and/or LDH) that normalized postoperatively." (PMID 31851466, 2020). "Alpha-fetoprotein (AFP), the most important tumor marker for HCC diagnosis, has been used for decades but results in a clinically unsatisfactory sensitivity of 40–65% and a specificity of 76–96%." (PMID 32377460, 2020). "Among them, our results revealed that ICG, AFP, PIVKA2, and tumor size had predictive prognostic power as the preoperative factors." (PMID 33272298, 2020). "The identified upper limit of tumor burden for downstaging was AFP ≤ 20 ng/mL and up-to-twelve as sum of HCC number and diameter; AFP = 21–200 and up-to-ten; AFP = 201–500 and up-to-seven; AFP = 501–1000 and up-to-five." (PMID 32075133, 2020). "Patients with AFP-NHCC often have mild clinical symptoms, so other tumor markers are indispensable for its diagnosis, especially in the early stage of the disease." (PMID 32190001, 2020). "In multivariate analysis, the parameters of preoperative CTC count, alpha-fetoprotein (AFP) and tumor diameter were independent predictors of MVI (P < 0.05)." (PMID 33129301, 2020).
tumor (continued). "Although the combined used of AFP + PIVKA-II showed a good performance for the detection of HCC, the added value of a non-invasive biomarker is represented by the ability to predict tumor development before imaging discovery." (PMID 33142893, 2020). "Then we explored the correlation between AFP, PIVKA-II serum level and several pathological features such as vascular invasion, tumor differentiation and size." (PMID 33292429, 2020). "MAPE age > 56.61 years, tumor size > 12.45 mm, HCV carrier status, and ln(AFP) > 1.954, are useful indicators for the early detection of small HCCs." (PMID 33193879, 2020). "Some variables differed between the groups, including age, ALT levels, tumor size, ALBI score, and AFP level." (PMID 32266136, 2020). "According to postoperative pathological and immunohistochemical markers, there were two epithelial cell groups in the tumor, one of which expressed CKs AE1/AE3, hepatocyte, TTF1, AFP, and CD10 and another expressing CK7 and CK19." (PMID 32967689, 2020). "In terms of tumor factors, about two thirds of the HCC tumors (68.5%) in the AFP group were in previously established blind spots of the US test, including hepatic dome, area under the rib, caudate lobe, and tip of the lateral segment of the left lobe." (PMID 32845895, 2020). "With regards to serum tumor marker, six of the seven HCC patients had AFP levels ≥20 ng/mL, whereas all the 11 patients diagnosed with benign nodules had AFP levels <20 ng/mL." (PMID 32640555, 2020). "Serum protein tumor markers like CEA, AFP, CA-125, CA-19.9, PSA, etc., have been used for decades to aid in the diagnosis and management of a variety of cancers." (PMID 32492934, 2020). "We constructed a prognostic nomogram with NUDT1 expression, AFP levels, vascular invasion, Child–Pugh classification, age, sex, AJCC staging, and tumor differentiation as variables." (PMID 32341205, 2020). "Tumor markers, including soluble IL-2 receptor, carcinoembryonic antigen (CEA) and alpha fetoprotein (AFP), were within the normal ranges." (PMID 33000344, 2020). "Alpha fetoprotein (AFP) > 100 ng/mL (OR = 3.027, p = 0.037) and tumor size (OR = 1.06, p = 0.001) independently predicted IDR." (PMID 32013112, 2020). "Univariate analysis of follow-up data showed that multiple tumor nodules, tumor size > 5 cm, MVI, AFP > 20 ng/ml and GLR > 56.0 were correlated with a shorter PFS and OS." (PMID 32070301, 2020). "Several biomarkers (alpha‐fetoprotein [AFP], carcinoembryonic antigen [CEA], etc) for tumour diagnosis have been developed and widely used in clinical practice; however, they are inefficient with low accuracy." (PMID 32783378, 2020). "In agreement with our findings, previous studies reported on the prognostic utility of baseline AFP and PIVKA-II, for patients with different tumor severities and treatment approaches." (PMID 32998218, 2020). "Other tumor markers, including carcinoembryonic antigen (CEA), alpha fetoprotein (AFP), and human chorionic gonadotropin (HCG), were within the normal ranges." (PMID 32725385, 2020). "We found that AFP and PIVKA-II had strong correlation with tumor size (measured by diameter) and differentiation as well as vascular invasion." (PMID 33292429, 2020). "As AFP is highly expressed in HCC tissues, its involvement in the tumor immune escape mechanisms remains unexplored." (PMID 32774373, 2020). "IHC analysis demonstrated that tumor cells was Vimentin (+), α-Inhibin (+), CD99 (+), Calretinin (+), SF-1(+), AE1/AE3 (+), CD10 (+), ER (+), PR (+), AFP (−), EMA (−), SMA (−), CK7 (−), Ki-67 (+60%)." (PMID 32629665, 2020). "Another study found that binding of AFP/AFPR leaded to Ca2+ influx, prompting DNA synthesis and enhancing tumor cell proliferation." (PMID 31897235, 2020). "This retrospective study is one of the few studies that assess the clinical utility of tumor markers CEA, CA19-9, CA125, AFP, NSE, CA15-3, and CYFRA21-1 for prognostic specification as well as for measuring the response to chemotherapy." (PMID 32582542, 2020).
tumor (continued). "Some factors were associated with the OS of HCC patients, including CTC-WBC cluster, tumor size, portal vein tumor thrombus, BCLC stage, AFP, and total CTCs." (PMID 33224869, 2020). "Markedly reduced Fas expression was also observed in AFP-positive HCC cells and human tumor samples." (PMID 33009373, 2020). "Meanwhile, AFP and PIVKA2 are reliable markers to predict patient outcomes reflecting tumor biology." (PMID 33272298, 2020). "As a result, we identified the top 6 (NLR, age, tumor size, APRI, PHT, PLR) and 12 (APRI, age, AFP, HBVDNA, tumor size, gender, PLR, CTP grade, BED10, PHT, LMR, and TNM stage) predictors for OS and PFS in order of relative importance." (PMID 33046985, 2020). "A Cox regression univariate analysis revealed that some factors were associated with the DFS of HCC patients, including CTC-WBC clusters, tumor size, portal vein tumor thrombus, BCLC stage, Edmondson stage, microvascular invasion, AFP level, and total CTCs." (PMID 33224869, 2020). "Serum alpha-fetoprotein (AFP) is a useful marker for YST, informative for monitoring response to chemotherapy and tumor recurrence." (PMID 32774158, 2020). "The sensitivity of serum miR-223-3p, AFP and combination in diagnosis of HCC according to tumor staging." (PMID 32330203, 2020). "In multivariable analysis, the size of the largest tumor >5cm (Adjusted odds ratio [AOR]: 3.74, 95% CI: 1.57–8.90, P = 0.003) and AFP >200 ng/mL (AOR: 3.11, 95% CI: 1.40–6.91, P = 0.005) was associated with poor responses to repeated TACE." (PMID 32130270, 2020). "The AFP, PIVKA-II concentration showed significant differences in well/moderate/poor differentiation as well as tumor size of HBV-related HCC." (PMID 33292429, 2020). "Our results were consistent with previous studies; higher serum AFP level, NLR or poorly differential tumor cell type had a positive correlation with the incidence of MVI among patients with HCC." (PMID 33251138, 2020). "In conclusion, our results demonstrate that DTA-expressing plasmid inhibited proliferation of HCC cells and DTA expression in an AFP-promoter-dependent manner and reduced the growth of HCC in vivo and decreased the tumor markers of AFP and DCP." (PMID 32085552, 2020). "In 2,079 patients of BIOSTAT‐CHF cohort, we measured six established tumour biomarkers: CA125, CA15‐3, CA19‐9, CEA, CYFRA 21‐1 and AFP." (PMID 32372544, 2020). "The conclusions about the relation between AFP, PIVKA-II and clinicopathologic features (such as vascular invasion, tumor differentiation and size) were different, even controversial." (PMID 33292429, 2020). "AFP is an established prognostic marker of both poorer HCC phenotype and more aggressive tumour biology." (PMID 32471447, 2020). "Aberrant glycans have also been shown to serve as non-invasive tumor biomarkers, such as carcinoma antigen 19–9 (CA19–9) in pancreatic cancer and α-fetoprotein (AFP) in hepatocellular carcinoma." (PMID 32620165, 2020). "The multivariable analyses indicated that the following factors were related to early relapse: AST, AFP, HBV DNA load, tumor capsule, MVI, and surgical margin." (PMID 32478080, 2020). "This AFP TCR bears properties that are expected to allow T cells, redirected with this TCR, to specifically differentiate between AFP levels on tumor and normal tissues." (PMID 32425926, 2020). "This is because variables such as the alpha-fetoprotein levels (AFP level), Child-Pugh score, and HBV status influence tumor heterogeneity." (PMID 32962762, 2020). "Two AFP-positive HCC patients, whose data of tumor size and metastasis status were missed, were excluded from the following analysis." (PMID 33014866, 2020). "The exact number of assessments for each tumour biomarker was as follows: CA125 (N = 2069), CA15‐3 (N = 2073), CA19‐9 (N = 2066), CEA (N = 2079), CYFRA 21‐1 (N = 2054) and AFP (N = 2078)." (PMID 32372544, 2020).
tumor (continued). "Serum PIVKA-II and AFP levels and the serum γ-GT/ALT ratio were positively correlated with tumour size in patients with HCC (r = 0.520, P < 0.001; r = 0.328, P < 0.001; r = 0.209, P = 0.001, respectively)." (PMID 32782270, 2020). "The ABCR score included baseline AFP ≥ 200 ng/mL, baseline BCLC stage, an increase in the Child-Pugh score by ≥2 points, and radiological tumor response after the first TACE." (PMID 33142892, 2020). "In terms of tumor-related factors, the separate AFP and US groups were more likely to have early stage HCC and to receive curative treatments than the combined AFP+US group (Ps<0.05)." (PMID 32845895, 2020). "According to univariate analyses of baseline variables, the ECOG score, the tumour size, the number of HCC nodules, PVTT, EHS, ascites, the AFP level, the albumin level, the total bilirubin level and the AST level were significantly associated with OS." (PMID 31815114, 2019). "In the multivariate analysis, the results indicated that tumor size, TNM stage, treatment exposure, serum AFP level, and albumin / CRP ratio were independent factors for HCC prognosis." (PMID 31164099, 2019). "AFP and β-HCG are serum tumor markers of testicular neoplasia that play important roles in diagnosis, treatment, prognosis, and follow-up." (PMID 30885154, 2019). "All of the four tumour parameters were found to be statistically significant on single variable models for the Glasgow index, however only two of them (MTD and AFP) were statistically significant in the final model (p<0.05)." (PMID 30662766, 2019). "In the univariate analysis of OS and DFS, the significant prognostic parameters are tumor size, TNM stage, treatment exposure, serum AFP level, serum CRP level, serum albumin level, albumin / CRP ratio, and platelet / CRP ratio." (PMID 31164099, 2019). "Confounders, major threat to the validity of this observational study were tumor capsule, maximal diameter, ALT, Age, tumor differentiation, CEA, CA19-9, AFP, which were selected by previous described procedures." (PMID 31632502, 2019). "Among tumor markers for the diagnosis of HCC, measurement of AFP has been performed for decades, although with some dispute regarding its significance." (PMID 31541423, 2019). "AFP level can give information about HCC since it is positively correlated with HBV infection, tumor size, low cellular differentiation, and reaches the highest level in the case of metastatic tumor." (PMID 31258835, 2019). "Alpha-fetoprotein (AFP) is a well-recognized tumor marker of HCC; however, an elevated serum AFP level is only found in approximately 60% of all newly diagnosed HCC patients." (PMID 31915469, 2019). "Global prognostic features included known prognostic markers in HCC, like alpha-fetoprotein and GPC3 expression in the tumor." (PMID 30922327, 2019). "Only a few plasma tumor markers, such as prostate specific antigen (PSA), cancer antigen 125 (CA125), and alpha-fetoprotein (AFP), have been clinically used for early stage cancer diagnosis in the United States." (PMID 31167407, 2019). "The RNA expression data from the TCGA_LIHC cohorts revealed that increased ESR1 mRNA expression correlated significantly with gender, age, serum AFP, TNM stage, tumor recurrence and tumor differentiation." (PMID 31410310, 2019). "In this study, GLR showed a positive relation with tumor size, tumor-node-metastasis (TNM) stage, microvascular invasion, early recurrence, and serum aspartate aminotransferase (AST) level, while the AFP value only correlated with drinking." (PMID 31165038, 2019). "Among different types of tumor markers, protein biomarkers, such as IMP2, AFP, B2M, CA15-3, CA19-9, CA-125, cytokeratin and so on, are especially welcomed due to its accessibility." (PMID 30755649, 2019).
tumor (continued). "Significant differences in the survival rate were seen in covariates with radiation (P < 0.001), tumor size (P = 0.022), lymph nodes (P < 0.001), distant metastasis (P < 0.001), AJCC Stage (6th) (P < 0.001), and AFP level (P < 0.003)." (PMID 30656831, 2019). "They show that age, ECOG, aetiology, tumour size, extra-hepatic spread, vascular invasion, log(bilirubin), log(AST), log(AFP), albumin and INR were statistically significant prognostic factors." (PMID 31182766, 2019). "The tumor markers for testicular tumor were all elevated (LDH, 1483 U/l; AFP, 810.88 ng/ml; and b-HCG, 506166 mIU/ml)." (PMID 30912892, 2019). "The results revealed that tumor size ≥1.5 cm, PTV ≥83.7 cm3, AFP ≥25.0 ng/ml, a low level of TNF-α, WBC, baseline and post-treatment TPLC and CLP counts except for post-treatment B cell value, were significantly associated with poor OS (p < 0.05 for each)." (PMID 31552194, 2019). "The BCLC classification system, AFP, and the MELD score are considered to be correlated with tumor burden, tumor biology, and degree of liver function, respectively." (PMID 31429755, 2019). "Positive expressions of AFP, Ki-67 and PCNA were detected by immunohistochemistry in tumor tissues, which were markedly upregulated by circRNA Cdr1as overexpression." (PMID 31581132, 2019). "Pretreatment ACR was correlated with tumor size, TNM stage, treatment exposure, and serum AFP levels." (PMID 31164099, 2019). "The levels of tumor markers, such as human chorionic gonadotropin (HCG), alpha-fetoprotein (AFP), and lactate dehydrogenase (LDH), were in the normal range before and after surgery." (PMID 31451109, 2019). "The results indicated that treatment exposure, TNM stage, and tumor size, have higher HR value than ACR and AFP, which mean that they have a greater weight in representing its prognosis." (PMID 31164099, 2019). "Univariate analysis indicated that tumor size, differentiation, HBV infection, AFP, portal vein invasion, TNM stage, metastasis, and CKS2 expression were associated with OS of HCC patients." (PMID 31781310, 2019). "And we also did ROC analysis on the four more regular tumor markers, the AUCs of CEA, CA19-9, CA125 and AFP were 0.632, 0.634, 0.716 and 0.575, respectively." (PMID 30755649, 2019). "The MoRAL score is calculated from serum AFP and PIVKA-II, and shows refined prognostication for tumor recurrence after LT." (PMID 31689972, 2019). "The tumor markers LDH (lactate dehydrogenase), AFP (alpha-fetoprotein) and β-HCG (human chorionic gonadotropin) produced by some of the cancer cells and measurable in serum contribute to establish the diagnosis, with LDH being the less specific marker." (PMID 31597402, 2019). "A univariate logistic regression models of the CRP groups (CRP≤10 and >10) provided distinct p-values for each of the four tumour parameters, and MTD, AFP, and PVT were found to be statistically significant (p<0.05)." (PMID 30662766, 2019). "Gstz1−/− mice exhibited promoted liver tumorigenesis with increased tumor masses, number of tumor nodules, and higher levels of alanine aminotransferase (ALT) and alpha‐fetoprotein (AFP) in serum." (PMID 31267557, 2019). "His bloods and tumour markers including carcinoembryonic antigen (CEA), cancer antigen (CA) 19-9 and alpha-fetoprotein (AFP) were normal." (PMID 30731302, 2019). "AFP level remained a prognostic factor for HCC even after accounting for demographics and tumor characteristics; however, further studies are needed to improve the prediction of HCC patient outcomes, especially among racial minorities." (PMID 31517445, 2019). "We also demonstrated that the AFP value was closely related to HCC differentiation, tumor size and vascular invasion in a previous study." (PMID 31295310, 2019). "The tumor markers -βhCG, AFP and LDH are useful in diagnosis, prognosis, assessing therapeutic response and detecting tumor recurrence." (PMID 31897390, 2019).